LINC00334 (long independently transcribed non-coding RNA 334)
Synonyms: C21orf89; NCRNA00334
Gene: Long non-coding RNA gene on chromosome 21 (45,234,308 to 45,264,548, forward strand). Ensembl gene ENSG00000182586.
Diseases named in the same sentence as LINC00334 in open-access papers:
LINC00334 is named in the same sentence as 2 diseases in open-access papers, as found by Europe PMC text mining. Sharing a sentence is not in itself a finding about the gene and the disease. The quoted sentences say what the papers report.
tumour (1 paper, 2024). "In comparison with peritumoral tissues (normal), MIR31HG showed elevated amounts in tumour tissues (tumour), while MIR9_3HG, LINC00334, MIR7_3HG, AC022915.2, AC048382.5, AC009315.1, AL079338.1, LINC01524, AC005520.2, AC245407.2, AC009690.2 and LINC01322 had lower levels." (PMID 39639610, 2024).
LINC00334 also shares sentences with these, for which no sentence is quoted: cancer (1 paper).